SOST (sclerostin)
Diseases named in the same sentence as SOST in open-access papers (continued):
Sharing a sentence is not in itself a finding about the gene and the disease.
periodontitis (continued). "In addition, it has been shown that the use of diode laser with SRP improves clinical parameters by reducing sclerostin (a bone formation inhibitor) levels in the GCF of patients with chronic periodontitis." (PMID 35706460, 2022). "Sclerostin trended higher in gingivitis but was similar in periodontitis and healthy sites." (PMID 34440994, 2021). "Periodontitis-induced sclerostin elevates the RANKL/OPG ratio and ERK1/2 in alveolar bone." (PMID 32708317, 2020). "Sclerostin, the osteocyte-expressed and secreted inhibitor of bone formation, can also be found at higher levels in the crevicular fluid from periodontitis patients and could be a more reliable measure for diagnosis or prognosis of disease than RANKL." (PMID 30924022, 2019). "Taken together, decreased sclerostin expression in osteocytes after intermittent PTH administration appears to be involved in the increase in bone formation observed in type 1 diabetic rats with periodontitis." (PMID 29544500, 2018). "PTH-induced bone formation may be related to the regulation of osteocytic sclerostin expression in type 1 diabetic rats with periodontitis." (PMID 29544500, 2018). "Together, our results suggest that the effect of SIM on tibial bone loss may be related to the inhibition of osteoclast formation and sclerostin expression in type 1 diabetic rats with periodontitis." (PMID 30413166, 2018). "In addition, sclerostin levels in gingival crevicular fluid are higher in patients with chronic periodontitis than those in healthy individuals." (PMID 29240821, 2017). "Therefore, the objective of this study was to determine the effect of infliximab (IFX), a TNF-α antagonist, on osteocytic RANKL and sclerostin expression in STZ-induced type 1 diabetes rats with periodontitis." (PMID 29240821, 2017). "Our study suggests that TNF-α might mediate osteocytic RANKL and the sclerostin expression in type 1 diabetes with periodontitis." (PMID 29240821, 2017). "Therefore, the attenuation of sclerostin-positive osteocytes in IFX treated rats implicates the stimulatory effect of TNF-α on osteocytic sclerostin expression in type 1 diabetes with periodontitis." (PMID 29240821, 2017). "Furthermore, wild type mice with periodontitis exhibit significant bone resorption compared to sclerostin knockout mice with periodontitis." (PMID 29240821, 2017). "Finally, it was also demonstrated that pharmacologic inhibition of SOST, using a SOST neutralizing monoclonal antibody, restored the alveolar bone destruction following experimental periodontitis in rats." (PMID 27257912, 2016). "Hence, the expression of sclerostin was found to be similar in both types of periodontitis." (PMID 37645545, 2023). "In summary, current studies demonstrate that sclerostin may contribute to the development of periodontitis by regulating the anabolism and catabolism of alveolar bone, and sclerostin inhibition during periodontitis could improve alveolar bone mass and repair the morphology of periodontal ligament." (PMID 35562828, 2022). "Protein levels of Sclerostin could be increased during the early period of tissue destruction, followed by a significant decrease when the initial stimulus has already disappeared in periodontitis sites." (PMID 34440994, 2021). "In addition, treatment with a TNF-α antagonist could reduce sclerostin expression in osteocytes in diabetic rats with periodontitis." (PMID 31341915, 2019). "Also in serum or in gingival biopsies, sclerostin was increased in chronic periodontitis patients." (PMID 30924022, 2019). "Quantitatively, ligature-induced periodontitis increased Osterix+RANKL and Sclerostin+RANKL colocalized cells in both the maxilla and mandible versus Sham, including after natural recovery (PD+RECOV)." (PMID 41583507, 2026). "Sclerostin and DKK1 act as the Wnt signaling inhibitors and are upregulated in patients with chronic periodontitis." (PMID 36297683, 2022).
periodontitis (continued). "In conclusion, Sclerostin and WNT-5a were detectable in the GCF of periodontitis, gingivitis and healthy patients." (PMID 34440994, 2021). "Data from clinical studies have shown that SOST is upregulated in periodontal tissues, saliva and GCF of chronic periodontitis patients when compared to healthy sites." (PMID 34440994, 2021). "Another osteocyte-secreted molecule, sclerostin, increases the RANKL/OPG ratio in periodontitis via ERK1/2-MAPK in alveolar bone." (PMID 32708317, 2020). "In brief, it can be concluded that osteocytes play a role in periodontitis through the expression of RANKL and sclerostin." (PMID 30924022, 2019). "Evaluation of SOST and DKK-1 in chronic periodontitis patients showed that both of these inhibitors were up-regulated in the periodontal tissues of these subjects (Napimogaet al., 2014)." (PMID 31031968, 2019). "Below, the recently discovered role of osteocytes as cellular players in periodontitis progression is discussed, highlighting both the RANKL and the sclerostin pathway." (PMID 30924022, 2019). "It was documented that SOST and DKK1 were upregulated in the periodontal tissues of chronic periodontitis subjects, suggesting a possible role of these molecules on periodontal tissues." (PMID 27257912, 2016). "Sclerostin serves as positive feedback for RANKL expression in inflammation progression, implying that sclerostin may have a promoting effect on periodontitis, furthermore, osteoclast might be conductive to this promotion process." (PMID 35562828, 2022). "The “strict” periodontitis subgroup produced median levels of SOST (140.00 pg), WNT-5a (2.4 pg) and TNF-α (44.7 pg) compared with the “strict” healthy group who exhibited levels of SOST (78.9 pg), WNT-5a (1.29 pg) and TNF-α (27.3 pg)." (PMID 35453967, 2022). "Considering the current knowledge in the field, we hypothesized that the total amount of Sclerostin and WNT-5a in GCF differ at sites with (i) chronic periodontitis, (ii) gingivitis and (iii) healthy periodontal tissues." (PMID 34440994, 2021). "In a study comparing the clinically relevant doses of the sclerostin antibody with bisphosphonates in an experimental periodontitis rat model after ovariectomy, no osteonecrosis developed and also less alveolar bone was lost." (PMID 30924022, 2019). "Interestingly, the low bone formation in type 1 diabetes rats with periodontitis is correlated with high osteocytic sclerostin expression, suggesting that bone formation might be suppressed in type 1 diabetes with periodontitis via high osteocytic sclerostin expression." (PMID 29240821, 2017). "The possible reason for the insignificance in sclerostin levels between SIII-GC and SIII-GB could be that, even though the rate of progression of bone destruction between the two grades of periodontitis are different, the mechanism of bone destruction involving the Wnt signaling pathway are similar." (PMID 37645545, 2023). "Targeting sclerostin and DKK1 could be an attractive adjuvant strategy for periodontitis treatment." (PMID 36297683, 2022). "Also, the classical view of histological changes during periodontitis does not consider the osteocyte as producer of the bone formation inhibitory protein sclerostin that inhibits the Wnt-signaling pathway." (PMID 30924022, 2019). "However, the effects of PTH on alveolar bone formation and osteocytic sclerostin expression of rats with both periodontitis and type 1 diabetes have been not determined." (PMID 29544500, 2018). "Sclerostin not only exerts similar negative outcomes on the formation of alveolar bone and bone-like tissues, including dentin and cementum, but also participates in the development of oral inflammatory diseases such as periodontitis, pulpitis, and peri-implantitis." (PMID 35562828, 2022).
postmenopausal osteoporosis (31 papers, 2013 to 2026). Metabolic disorder associated with fractures of the femoral neck, vertebrae, and distal forearm. "Neutralizing sclerostin antibodies (Scl-Ab) mitigate bone loss and promote bone formation to address fracture risk in postmenopausal osteoporosis." (PMID 42027593, 2026). "Sclerostin deficiency leads to rare bone sclerosing disorders, while elevated levels of sclerostin are implicated in the pathogenesis of metabolic bone diseases like postmenopausal osteoporosis." (PMID 40647466, 2025). "Antibodies targeting sclerostin can ameliorate postmenopausal osteoporosis but present some cardiovascular risk." (PMID 35869074, 2022). "Loss-of-function mutations in the SOST gene are associated with high bone mass, and the sclerostin antibody Romosozumab is a recently approved drug for the therapy of postmenopausal osteoporosis." (PMID 35267956, 2022). "A study of 639 Chinese women with postmenopausal osteoporosis previously showed that SOST polymorphic variant correlates with change in the BMD level in the lumbar spine and femoral neck after 12 months of alendronate therapy (P<0.05)." (PMID 31437227, 2019). "In addition, SOST/sclerostin expression is altered in certain pathogenic conditions, including postmenopausal osteoporosis, osteoarthritis and rheumatic joint disease." (PMID 33419004, 2021). "Sclerostin acts as an internal antagonist of the bone anabolic Wnt signaling pathway, and it is a novel bone anabolic target for the treatment of postmenopausal osteoporosis." (PMID 40429697, 2025). "Humanized anti-sclerostin antibody, romosozumab, was approved for treatment of postmenopausal osteoporosis by the US Food and Drug Administration (FDA), but with a black-box warning on cardiovascular risk." (PMID 40429697, 2025). "Some anti-sclerostin antibodies, such as romosozumab and blosozumab, are being tested in clinical trials for the treatment of postmenopausal osteoporosis via neutralizing SOST, and the relevant trial outcomes are promising." (PMID 38393416, 2024). "Due to its enhanced anabolic effect on bone formation and its diminished catabolic effect on bone resorption, sclerostin antibody therapy has been proposed as a new treatment for postmenopausal osteoporosis." (PMID 37121919, 2023). "Monoclonal human Ab against sclerostin, ROMO, that targets the Wnt signaling pathway was recently approved as a new and potent anabolic agent for the treatment of women with postmenopausal osteoporosis at high risk of fracture." (PMID 38130761, 2023). "Clinically, the humanized therapeutic sclerostin antibody (romosozumab) demonstrated the bone anabolic potential against postmenopausal osteoporosis, whereas imposed severe cardiac ischemic events (BRIDGE and ARCH) 5-8." (PMID 35966595, 2022). "An antibody targeting sclerostin for the treatment of postmenopausal osteoporosis was approved by the U.S. Food and Drug Administration, with a boxed warning for cardiovascular risk." (PMID 35869074, 2022). "Wnt-catenin signaling antagonists sclerostin and dickkopf-related protein-1 (Dkk-1) inhibit bone formation and are involved in the pathogenesis of postmenopausal osteoporosis (PO)." (PMID 34034718, 2021). "The past decade had witnessed frequent breaks in therapeutic development targeting LRP5 signaling, namely, the anti-DKK1 and anti-sclerostin molecules in the treatment of postmenopausal osteoporosis." (PMID 34796178, 2021). "Neutralizing antibodies to sclerostin have had great success in phase III trials for postmenopausal osteoporosis, and a sclerostin neutralizing antibody—Romosozumab—was recently approved for clinical use in Japan, the US, South Korea, Canada, and Australia." (PMID 31505764, 2019). "The results of this study show the possible role of allelic combinations of SOST rs1234612, PTH rs7125774, FDPS rs2297480, and GGPS1 rs10925503 gene variants in the individual response to BPs treatment in women with postmenopausal osteoporosis." (PMID 31437227, 2019).
postmenopausal osteoporosis (continued). "The main finding in our study was that cortical bone matrix contents of SOST and DKK1 in postmenopausal osteoporosis were positively associated with bone mass and strength." (PMID 31197079, 2019). "Trials using a sclerostin antibody have shown efficacy in increasing BMD in patients with postmenopausal osteoporosis." (PMID 25802521, 2015). "Rationale: Sclerostin inhibition demonstrated bone anabolic potential in osteogenesis imperfecta (OI) mice, whereas humanized therapeutic sclerostin antibody romosozumab for postmenopausal osteoporosis imposed clinically severe cardiac ischemic events." (PMID 35966595, 2022). "In a study conducted using postmenopausal osteoporosis and male osteoporosis animal models, bone densities of trabecular and cortical bones were shown to markedly increase in a group administered with anti-sclerostin antibody." (PMID 31698687, 2019). "Consistent with previous reports, serum sclerostin levels were significantly elevated in OVX mice, which is characteristic of postmenopausal osteoporosis." (PMID 41159395, 2025). "Novel osteoanabolic therapies such as the PTH-related protein analogue abaloparatide and the anti-sclerostin antibody romosozumab, which have been approved for the use in postmenopausal osteoporosis, have not yet been evaluated in GIO." (PMID 35432217, 2022). "To demonstrate the role of Wnt/β-catenin canonical pathway in postmenopausal osteoporosis, we evaluated the levels of serum β-catenin, OPG, RANKL, sclerostin, and bone turnover markers in postmenopausal osteoporotic patients and compared them to those in postmenopausal nonosteoporotic women." (PMID 23710175, 2013). "The anti-receptor activator of NF-kappaB ligand antibody denosumab treatment was associated with significant increases in serum sclerostin levels in postmenopausal osteoporosis; however, others reported serum sclerostin concentrations was not affected by denosumab or zoledronic acid medication." (PMID 30949129, 2019).
Insulin resistance (28 papers, 2018 to 2025). Increased resistance towards insulin, that is, diminished effectiveness of insulin in reducing blood glucose levels. "Clinical investigations have corroborated these preclinical findings, demonstrating that sclerostin levels are significantly higher in prediabetic individuals compared to controls and are associated with insulin resistance." (PMID 40044973, 2025). "A part from actions on bone, sclerostin has metabolic effects and higher sclerostin was associated with higher body mass index, fat mass, and insulin resistance." (PMID 39078512, 2024). "Since it is a cross-sectional study it does not provide information related to the causative relationship between sclerostin and insulin resistance/sensitivity." (PMID 36004027, 2022). "Circulating levels of sclerostin were found to correlate with risk of fracture, homeostatic model assessment for insulin resistance (HOMA-IR), body mass index (BMI), and fat mass as well." (PMID 33671861, 2021). "In particular, sclerostin is associated with lower levels of insulin, alongside reduced insulin resistance in diabetic patients compared to controls." (PMID 33801212, 2021). "This suggests that observed association between sclerostin levels and insulin resistance can indirectly reflect the deteriorative effect of higher BMI on insulin sensitivity." (PMID 32592042, 2020). "Sclerostin is associated with insulin resistance and rises significantly with declining renal function and may play a protective or regulatory role in vascular and mineral metabolism." (PMID 40731833, 2025). "The main objectives of the study are: to determine whether sclerostin is associated with glycemic parameters, serum insulin levels, insulin resistance/ sensitivity, beta-cell function, and adipose tissue insulin resistance (Adipo-IR)." (PMID 36004027, 2022). "However, it should be noted that our study is the first study assessing the association between sclerostin levels and nutritional status, insulin resistance and hormone levels in young women with PCOS." (PMID 32592042, 2020). "In contrast, serum insulin levels were significantly elevated in sclerostin-overexpression mice, indicating the occurrence of insulin resistance." (PMID 40149867, 2025). "Increased sclerostin levels and a link between sclerostin levels and insulin resistance in skeletal muscle, liver, and adipose tissue were investigated in a cross-sectional study of people with prediabetes only." (PMID 36004027, 2022). "There are very few studies worldwide that showed the correlation of sclerostin with insulin resistance in diabetic patients." (PMID 36004027, 2022). "We evaluated the correlation between serum sclerostin and anthropometric parameters, metabolic parameters related to glucose (homeostasis model assessment of insulin resistance [HOMA–IR]), lipid, and bone metabolism (osteocalcin and 25-hydroxy vitamin D)." (PMID 34572220, 2021). "Even in prediabetes, when insulin resistance and secretion are first altered, circulating sclerostin is elevated and positively correlated with fasting glucose production and metrics of insulin resistance." (PMID 33776907, 2021). "In 94 morbidly obese patients undergoing laparoscopic sleeve gastrectomy (SG), over-time changes in anthropometric and biochemical measures—including insulin resistance (IR) indexes—were correlated with serum sclerostin levels." (PMID 33671861, 2021). "Plasma sclerostin levels were significantly higher in the subgroup with insulin resistance [0.65 (interquartile range 0.53–0.77) vs. 0.52 (0.46–0.58) ng/mL; p < 0.001], while similar concentrations were observed in subgroups with FAI below and above median." (PMID 32592042, 2020). "The aim of this study was to evaluate the circulating sclerostin levels with nutritional status, insulin resistance and hormonal disturbances in women with polycystic ovary syndrome (PCOS)." (PMID 32592042, 2020).